TNF (tumor necrosis factor)
Diseases named in the same sentence as TNF in open-access papers (continued):
Sharing a sentence is not in itself a finding about the gene and the disease.
Granuloma (continued). "Not only was the expression of IL6 and TNF lower in late lesions, but it was confined to the outer edges of the generally circular granulomas." (PMID 20824205, 2010). "IL-1 favours a TH1 immune response and has been shown to play an important role in the formation of granulomas along with TNF-α." (PMID 19445695, 2009). "The main findings were a strong presence of TNF-α positive cells in necrotic granulomas, particularly in granulomas from HIV positive patients, where increased necrosis has previously been described." (PMID 19156215, 2009). "While the presence of necrosis did not significantly influence the grade of IL-12 mRNA positivity, IFN-γ, TNF-α and IL-4 mRNA expression were markedly upregulated in necrotic granulomas." (PMID 19156215, 2009). "The central core of the granulomas and the surrounding tissue showed strong reactivity for tumor necrosis factor-α (TNF-α)." (PMID 18477401, 2008). "Granuloma formation in sarcoidosis is mediated by increased secretion of interferon-gamma, interleukin-2, and tumor necrosis factor-alpha." (PMID 18226232, 2008). "The antimycobacterial immune response was characterized by well-formed granulomas with a low organism load, increased CD4/CD8 ratio in the granulomas, and marked TNF-α production." (PMID 18477401, 2008). "We assume instead that a certain concentration of anti-TNF molecules are present in the lung where granulomas would begin to form in response to infection." (PMID 17953477, 2007). "The establishment of granulomas is the manifestation of a vigorous cell mediated immune response, which is crucial for inhibiting mycobacterial growth and depends on TNF." (PMID 16285886, 2005). "Many cytokines play a crucial role in the formation of granulomas, including TNF-α and IFN-γ, and some immunosuppressive molecules may also be important mechanisms." (PMID 40520371, 2025). "Indeed, the PBMCs’ transcriptomic profile revealed enrichment in the gene set involving the JAK-STAT and TNF signaling pathways, widely acknowledged as fundamental in granuloma development and maintenance." (PMID 39996765, 2025). "Enrichment analysis revealed upregulated immunological pathways related to granuloma formation in pulmonary sarcoidosis PBMCs, including T helper 17 and tumor necrosis factor-alpha signaling pathways, IL-1B, IL-6, and IL-17 production, and response to external stimuli." (PMID 41463010, 2025). "Furthermore, anti-TNF-α therapy impairs the host defense against infection, particularly by disrupting granulomas formation and maintenance." (PMID 40370406, 2025). "However, M. marinum infection of zebrafish larvae showed that TNF’s major impact on granulomas is through decreased microbicidal activity within macrophages and an acceleration of the overall infection timeline." (PMID 40304497, 2025). "TNF blockade disrupts these granulomas, allowing Mycobacterium tuberculosis to proliferate." (PMID 41458842, 2025). "Mice deficient in T cell TNF develop extensive necrosis without defined granulomas, leading to widespread lung damage." (PMID 40427602, 2025). "In humans, multinucleated cells in granulomas stain positive to TNF-α, but its expression is low." (PMID 41019663, 2025). "In individuals with inadequate adaptive response in case of HIV infections, newborns or people undertaking anti-TNF-α therapies, granulomas become necrotic with a caseous center (soft, cheese-like appearance), which results in dissemination of the infection to other parts of the host." (PMID 40406522, 2025). "The exact mechanisms underlying this phenomenon remain unclear; however, it is hypothesized that TNF-α inhibition disrupts the maintenance of granulomas, leading to immune dysregulation and the subsequent development of granulomatous inflammation." (PMID 40351964, 2025).
Granuloma (continued). "TNF, a well-known proinflammatory cytokine produced mainly by monocytes, macrophages, and T cells, is involved in the inflammatory processes and, in TB, is crucial for the formation of a well-organized granuloma and host protection." (PMID 39530101, 2024). "Yet, there are case reports of caseating granulomas (often a sign of high Mtb burden) found in active TB in the presence of TNF blocking agents, indicating that granulomas that form despite TNF deficiency are not protective." (PMID 39717773, 2024). "However, significant differences were found in the expression of TNF, a functional M1 marker, which was expressed in higher levels in Silirum® induced granulomas." (PMID 38352038, 2024). "Granulomas may spontaneously resolve or persist, and may progress to fibrosis via high levels of TNF and mononuclear phagocytes (MNPs) and activation of fibroblasts, myofibroblasts, and collagen formation." (PMID 38202248, 2023). "TNF-α immunolabeling was greater in granulomas of calves observed in the cytoplasm of epithelioid MΦs, MGCs, and some fibroblasts found in cellular areas of granulomas and extracellularly, with greater intensity around necrotic sections and less intensity in the periphery of the lesion." (PMID 37180066, 2023). "IVIG, topical and systemic glucocorticoids, tacrolimus, TNF-α inhibitors have been used with variable success however a patient who underwent allogeneic hematopoietic stem cell transplantation (HCT) had complete remission from granulomas." (PMID 36891233, 2023). "TNF-α and IL-1α are the predominant contributors of granuloma formation." (PMID 38481606, 2023). "TNF is also crucial in the formation and maintenance of granulomas." (PMID 38288122, 2023). "Our single-cell transcriptomics and functional characterization demonstrate that ACE expression specifies a MΦ population that has distinctive cellular features, functional properties, and TNF regulation compared to other types of MΦs in STm granulomas and infected spleens." (PMID 36608122, 2023). "For instance, a prior study utilizing this in vitro model indicated that TNFα production is higher in sarcoidosis granulomas formed by PBMCs in response to PPD-coated beads compared to identically treated PBMCs from disease-free controls or latent TB treated with PPD-coated beads." (PMID 37021060, 2023). "An unknown antigen is first presented to CD4+ T-lymphocytes that trigger T-helper 17 (Th17)-related cytokines, interleukin-17A (IL-17A), regulatory T-cells, and tumor necrosis factor (TNF), a proinflammatory cytokine, to produce granulomas." (PMID 38202248, 2023). "Therefore, the expression of TNF-α can explain why the granulomas were still tight in our histology analysis." (PMID 37868350, 2023). "Anti-TNF-α therapy has been successful to treat extrapulmonary granulomas in CVID." (PMID 36891233, 2023). "Limitations of this study include the inter-sample variation in disease activity based on the in vitro granuloma model and also based on well-established disease phenotypes such as Lӧfgren’s (self-limited disease) and non-Lӧfgren’s (progressive) and related TNFα responses." (PMID 37021060, 2023). "The production of TNF and IL1-β by innate immune cells, the development of effective Th1 responses characterized by IFN-γ and TNF production, as well as the formation of stable granulomas, have all been shown to be critical for the host to control bacterial replication and dissemination in TB." (PMID 35669122, 2022). "Later, this model was transferred to C3Heb/FeJ mice, leading to the development of necrotic granulomas in the lung, meaning that the infection may reactivate under anti-TNF-α antibody treatment." (PMID 36557586, 2022). "Moreover, IFN-gamma and TNF-alpha are also involved in the formation of granuloma, in which Mtb can be contained." (PMID 35976976, 2022). "The expression of TNF-α is indicative of granuloma destruction." (PMID 35025927, 2022).
Granuloma (continued). "As a pleiotropic cytokine, TNF-α plays a multifaceted role during Mtb infection including attracting immune cells to the site of infection through a cascade reaction and maintaining granulomas to prevent Mtb from spreading out from the diseased tissue." (PMID 35651754, 2022). "Anti-TNF-α therapy compromises the physiological immunoinflammatory responses mediated by TNF-α and may alter the formation and maintenance of granulomas, leading to TB reactivation or spread." (PMID 34996655, 2022). "Moreover, there is a seemingly contradictory point between the negative regulation of FBXW7 on TNF-α vs FBXW7-mediated granulomas formation in this study." (PMID 35651754, 2022). "Supplementation of TNF-α and IFN-γ may attenuate the TNF inhibitor-induced resolution of granulomas." (PMID 36159650, 2022). "TNF-α is critically important for controlling bacterial growth during infection with M. tuberculosis due to phagocyte-activating functions and has an active role in the formation of granulomas." (PMID 34835417, 2021). "TNF, an essential component to the immune system’s response, is released by macrophages and T cells to stimulate the release of cytokines that promote the creation and maintenance of granulomas." (PMID 33933122, 2021). "In addition, TNF-α promotes apoptosis of Mtb-infected alveolar macrophages and plays a role in the formation and maintenance of granulomas." (PMID 34563261, 2021). "Additionally, a marked decrease in TNF-α concentrations was observed, this leads to the conclusion that granuloma formation was worsened due to low levels of TNF-α." (PMID 33172001, 2020). "The probability of a cytotoxic T cell being recruited to the granuloma site is significantly negatively correlated with the number of fibroblasts suggesting that high levels of CD8-type cytokines (for example TNFα) in the granuloma reduce the probability of a granuloma becoming fibrotic." (PMID 33370784, 2020). "Similar to anti-TNF-α, bevacizumab treatment of infected rabbits has been shown to promote vascular normalization, to improve small molecule delivery, and to decrease hypoxia in TB granulomas." (PMID 31936156, 2020). "TNF-α stimulation induced miR-889 upregulation in granulomas." (PMID 31992621, 2020). "In addition, TNF-α is also of great importance to leucocyte recruitment, which makes contributions to granulomas formation." (PMID 32176727, 2020). "In addition, TNF-α plays a key role in granuloma formation and maintenance of the integrity of the granuloma." (PMID 31936156, 2020). "TNF-α seems to be involved in formation and maintenance of granuloma." (PMID 32937808, 2020). "Furthermore, the use of anti-TNF antibodies in patients highlights the role of TNF in granuloma formation." (PMID 32411623, 2020). "However, it has been suggested that cytokines including IL-2, IL-7, IL-8, IL-12, IFN-γ, TNF-α, and GM-CSF have an important role in initiation and continuation of granuloma formation." (PMID 32350353, 2020). "TNF-α induces autophagy and is crucial for the formation of well-organized granulomas." (PMID 33057074, 2020). "Based on these cases, together with this report, it is possible to understand the complex role of TNF-a in the recruitment of histiocytes and formation of granulomas, which may help to focus future prospective NL treatments on this subset of patients." (PMID 31789246, 2019). "Thus, it was demonstrated that TNF-α promotes the production of chemokines and chemokine receptors, and also an expression of adhesion molecules, which affect the formation of granulomas in M. tb-infected tissues." (PMID 31888124, 2019). "For example, Hif-1α mediated TNF activation may be pertinent in later TB infection situations where granulomas have stabilized Hif-1α due to necrotic and hypoxic centers." (PMID 31611882, 2019).
Granuloma (continued). "As tumor necrosis factor-alpha (TNF-α) plays an important role in both formation and maintenance of sarcoidal granulomas, anti-TNF-α may provide a therapeutic option to patients with sarcoidosis." (PMID 31731423, 2019). "We provide evidences that the anti-TNF-α mediated-decrease of MGC in granuloma may involve an IL-10-dependent defect of cell fusion in the case of etanercept and may result from macrophage apoptosis induction in the case of adalimumab." (PMID 31475008, 2019). "TDM induces pulmonary granuloma formation and inflammation in mice by stimulating production of pro-inflammatory and T helper type 1 (Th1)-related cytokines such as tumor necrosis factor (TNF)-α, which represents many aspects of natural MTB infection in lungs." (PMID 29500453, 2018). "Hence, the aim of this study was to characterize the cells in human cherubism granulomas, to determine the osteoclastic characteristics of the multinucleated giant cells and to investigate the potential role of TNF-α in human cherubism." (PMID 30236129, 2018). "NAC-treatment of granulomas also resulted in downregulation in the production of TNF-α." (PMID 30258443, 2018). "In granulomas, IL-4 expression was significantly higher than IL-6 (p=0.001) and TNF-α (p=0.001)." (PMID 29898177, 2018). "Low expression of TNF-α was observed in both granulomas and cysts." (PMID 29898177, 2018). "In two patients, treatment with TNF inhibitors led to a partial regression of granulomas." (PMID 30279689, 2018). "In corroboration, our group showed that TNF-α-deficient mice are highly susceptible to P. brasiliensis infection, are not able to mount organized granulomas, and have a great amount of fungus in the lesions and high mortality rates." (PMID 28871251, 2017). "In both TNF−/− and etanercept-treated mice, liver granulomas were significantly larger." (PMID 29184553, 2017). "We studied the effect of an anti-inflammatory/immunosuppressive anti-TNFα treatment, which accelerates bacterial growth in the tissues and inhibits or reverses the formation of granulomas, on the efficacy of ampicillin and ciprofloxacin during a systemic Salmonella enterica infection of the mouse." (PMID 28087648, 2017). "In the course of granuloma maturation, the recruitment of phagocytes and lymphocytes is triggered by various cytokines and chemokines that are initially produced by infected macrophages, as TNF-α." (PMID 28871251, 2017). "Indeed, during early infection, TNF−/− mice showed inability to control M. tuberculosis infection, with rapid, exacerbated lung inflammation, and many granulomas with large necrotic areas." (PMID 29184553, 2017). "IL-6 and TNF-α are pro-inflammatory cytokines which have a role in granuloma formation." (PMID 28859607, 2017). "Role of TNF-α in the formation and maintenance of granuloma has been extensively reported." (PMID 28694808, 2017). "More extensive granulomas may respond to combination therapy (e.g. topical steroids plus IV gamma globulin therapy), systemic inhibitors of tumor necrosis factor (TNF-alpha) or direct injection of steroids into the site of the granulomatous lesions." (PMID 27884168, 2016). "T cell cytokine production in granulomas was higher in high risk compared to low risk macaques in the absence of TNF neutralization." (PMID 27379816, 2016). "The authors suggested that suppression of TNFα and interleukin 1 (IL-1) and interleukin 6 (IL-6) by the nicotine in tobacco smoke may in turn suppress granuloma formation in the population studied." (PMID 26422615, 2015). "Indeed, in immunocompetent subjects, clearance of internalized Cryptococcus is thought to depend on T helper 1 mediated response which results in formation of a granuloma and production of TNF-α and Interferon gamma (IFNγ)." (PMID 26688618, 2015). "There were T cells present that were producing both TNF and IL-2 in a subset of granulomas." (PMID 25611466, 2015).
Granuloma (continued). "Tumor necrosis factor-α (TNF-α) is produced by infected macrophages and plays an important role in the accumulation and differentiation of macrophages into the highly bactericidal epithelioid cells present in granulomas." (PMID 24967387, 2014). "Administering anti-TNFα medication in humans, however, does not appear to suppress granulomatous inflammation or cause disassembly of existing granulomas more effectively than corticosteroids alone." (PMID 25309534, 2014). "The increased TNF levels might possibly even be a consequence of the neutrophil microabscesses within CGD granulomas." (PMID 25188296, 2014). "When confined in granulomas for a long time, Mtb has to face a predominant Th-1 immune response and high expression of TNF-α; therefore, biosynthesis of SL and PAT precursors may be associated with mechanisms of immune evasion." (PMID 23472191, 2013). "TNF-α is important for establishing granulomas and the localized control of M.tb." (PMID 22719887, 2012). "We therefore utilized C3HeB/FeJ mice, which develop well-organized and hypoxic TB granulomas, with central caseous necrosis, and evaluated whether adjunctive TNF-α inhibition could hasten bacterial clearance." (PMID 22761866, 2012). "We therefore utilized C3HeB/FeJ mice, which develop well-organized and hypoxic TB granulomas with central caseous necrosis, and evaluated whether adjunctive TNF-α inhibition combined with standard TB treatment could hasten bacterial clearance." (PMID 22761866, 2012). "At the end of chemotherapeutic treatment (day 63 p.i.), WT and Tm-TNF mice had pulmonary pathology characterized by well-defined granulomas and clear alveoli whereas TNF−/− mice displayed higher inflammation characterized by peri-vascular and peri-bronchiolar inflammation." (PMID 22132068, 2011). "Development of pathology subsequent to withdrawal of chemotherapy (day 133 p.i.)continued to show well-defined granulomas in WT and Tm-TNF mice with clear alveoli, whereas TNF−/− mice now presented with excessive inflammation with no defined granulomas and limited alveolar space." (PMID 22132068, 2011). "From these studies the role of TNF in the formation of granuloma was demonstrated." (PMID 20961459, 2010). "Finally, we used the model to predict and analyze the effects of TNF-neutralizing drugs with different properties on the availability of TNF within a developed granuloma." (PMID 20463877, 2010). "Therefore, we develop a mathematical model based on an experimental model of granuloma developed in mice to predict TNF availability in a granuloma." (PMID 20463877, 2010). "The reduced production of TNF-α in the M. tuberculosis H37Rv infected cows is in agreement with the lack of visible pathology and reduced virulence as TNF-α has been implicated in murine models in formation and maintenance of granulomas." (PMID 20049086, 2010). "Granuloma formation and granuloma maintenance are critically dependant on the presence of TNF." (PMID 20652022, 2010). "Oxidative stress may be involved even in the very early stages of granuloma formation, as oxidants may stimulate macrophages to the production of TNF-α and other cytokines indispensable for granuloma formation." (PMID 20420721, 2010). "Granuloma formation also requires the presence of TNF, IL-2, IL-12, and inflammatory cytokines, such as monocyte chemotactic protein-1(MCP-1), and macrophage inflammatory protein-α (MIP-α), which collectively are involved in recruiting host cells to the site of infection leading to inflammation." (PMID 19946453, 2009). "However, infliximab poses a risk for reactivation of latent granulomatous infections by disrupting established granulomas; this occurs due to the neutralization of soluble TNF that is essential for the formation and maintenance of a granuloma." (PMID 19830122, 2009). "Membrane TNF is sufficient for the development of granulomas." (PMID 16285886, 2005).